CGAS (cyclic GMP-AMP synthase)
Diseases named in the same sentence as CGAS in open-access papers (continued):
Sharing a sentence is not in itself a finding about the gene and the disease.
tumor (continued). "With the increased expression of PD-L1, MHC-I, and CRT in tumor cells, cGAS/STING overexpression changes tumor immunogenicity and improves anti-PD-L1 treatments in in vitro and in vivo mice models." (PMID 36831197, 2023). "Given the critical role of PRMT1 in cGAS-dependent DNA sensing signaling and immune suppression in human and mouse tumor cells, we next examined the potential of PRMT1 as a target of cancer immunotherapy." (PMID 37193698, 2023). "It was shown that cGAS-STING driven type I interferon signaling is required for CXCL10/CCL5-dependent T cell recruitment to MMRd tumor." (PMID 37492581, 2023). "Unlike normal cells, cancer cells are rich in self DNA and cytoplasmic dsDNA, a byproduct of genomic instability, which activate the cGAS/STING pathway to promote or inhibit tumor development." (PMID 37354378, 2023). "The influence of GPC3144‐152 loading and/or cGAS silencing on the tumor growth, apoptosis and cGAS/STING signaling was tested by immunohistochemistry, immunofluorescence, flow cytometry, and Western blot." (PMID 37986544, 2023). "We identified plant-derived mitochondrial DNA (mtDNA), upon internalized into TAMs via the vesicles, as a major effector molecule to induce the cGAS-STING pathway driving the shift of pro-tumor macrophages to anti-tumor phenotype." (PMID 36879291, 2023). "Conversely, restoration of the normal cGAS-STING pathway boosts T-cell recognition of melanoma cells (a typical immunologically “cold” tumor)." (PMID 38139802, 2023). "This showed a positive correlation between cGAS and DNA‐PKcs protein levels and increased levels of both proteins with tumor grade." (PMID 36574362, 2023). "The ROS and 56MESS can severely damage the DNA and mitochondria and thus release dsDNA to activate cGAS‐STING pathway to induce the anti‐tumor effect." (PMID 37807827, 2023). "Studies with intratumoral administration of STING agonists further demonstrated profound tumor regression and substantial systemic immune responses, emphasizing cGAS-STING induction as an attractive therapeutic strategy for cancer." (PMID 38022587, 2023). "Taken together, these data demonstrated that the tumor‐derived HMGB1‐gDNA complex engaged in activation of the cGAS‐STING‐type I IFNs and NF‐κB pathways that further primed the inflammasome, which was finally activated by the tumor‐derived oxLDL in DCs." (PMID 37786300, 2023). "Secondly, previous studies have shown that DDR inhibitors trigger tumor immune responses through the cGAS-STING pathway." (PMID 37109350, 2023). "It has been suggested that cGAS downregulation is an immune escape strategy harnessed by tumor cells." (PMID 36574362, 2023). "The full scope of pro-tumorigenic cGAS–STING functions likely involves the concerted action of multiple components of the tumour microenvironment (TME), beyond cancer cells." (PMID 36876871, 2023). "This promising cGAS-STING regulating function is widely used for the development of various therapeutic anti-tumor strategies based on MnO2 nanomaterials." (PMID 37153576, 2023). "Tailor‐designed ZnFe2O4‐based nanosystem can respond to the tumour microenvironment and stimulate anti‐tumour immune responses by enhancing the cGAS/STING pathway." (PMID 38264691, 2023). "Genomic instability can induce an anti-tumour immune response via activation of the cGAS-STING pathway following the formation of micronuclei (MN)." (PMID 37640708, 2023). "In summary, the tailor‐designed ZnFe2O4‐PTX@CCM realized tumour cell targeting and ensured the induction of cytosolic DNA, improvement of cGAS‐DNA phase separation, and inhibition of mitotic process in tumour cells." (PMID 38264691, 2023). "Damaged nucleic acids released from dying tumor cells, regarded as DAMPs, can activate the cGAS-STING pathway and induce the release of type I IFNs, enhancing antitumor immunity." (PMID 37153627, 2023).
tumor (continued). "The cGAS-STING cascade is primarily stimulated in tumor cells and/or DCs and is critical to sense tumor cell–derived cytosolic DNA signal, triggering type I IFNs secretion, induce TLS formation, and promote antitumor killing by T cells and NK cells." (PMID 37768208, 2023). "Mechanistically, ATM inhibition greatly upregulated Gal-9 expression and secretion in a variety of human and murine tumor cells via the cGAS-STING-interferon β (IFNβ) innate immune pathway." (PMID 36778120, 2023). "Remarkably, C176 significantly increased tumor growth and tumor weight, suggesting that stimulation of cGAS/STING axis contributes at least in part to the tumor-suppressive effect of Trabid deficiency." (PMID 37237031, 2023). "Recent studies showed that tumor models with MLH1 deficient (dMLH1) accumulate cytoplasmic DNA and produce IFN-β in a cGAS-STING-dependent manner due to failure to repair damaged DNA." (PMID 37122745, 2023). "Radiation therapy is another local therapy to activate anti-tumor immunogenicity in the tumor microenvironment through the cGAS-STING pathway and subsequent CD8+ T cell activation." (PMID 37007160, 2023). "Further investigation of this and other aspects of cGAS–STING signalling in distinct compartments of the tumour microenvironment is likely to provide valuable insight enabling tailored targeting of cGAS–STING-driven signalling." (PMID 36876871, 2023). "Given the promising potential of the activated cGAS-STING signalling pathway in anti-tumour therapy, various STING agonists are being developed as anti-cancer drugs." (PMID 37448962, 2023). "Multifunctional nanoparticles are designed to play a role in tumor immunotherapy by inducing pyroptosis and activating the cGAS–STING pathways." (PMID 37342347, 2023). "This not only permits cGAS–STING activation within the TME of CIN-high tumours with defective DNA sensing pathways, but also offers ample opportunity for cancer cells to intercept or fine-tune cGAS–STING signal transmissions to their benefit." (PMID 36876871, 2023). "In this study, we maximized oxidized endogenous tumor mitochondrial DNA-mediated cGAS-STING activation for cancer immunotherapy by using ultrasound responsive chemotherapeutics LID." (PMID 37391428, 2023). "There is also emerging evidence that chronically activated cGAS/STING signaling can induce an immunosuppressive tumor microenvironment." (PMID 37354378, 2023). "Subsequently, cGAS recognizes the DNA source and responds quickly to activate the downstream cascade reaction to eliminate tumor." (PMID 37834184, 2023). "The cGAS-STING pathway plays a crucial role in the anti-tumor T cell response and radiation-induced anti-tumor response." (PMID 37781382, 2023). "We tested if cGAS KO in tumor cells, which will deplete the source of cGAMP to activate host STING, will abolish the therapeutic effect of macrophage PP2Ac deficiency." (PMID 36757811, 2023). "It has recently been reported that tumor cells with CIN rely on the cGAS-STING pathway to promote cancer cell survival through the STING-mediated NF-κB activation, which in turn induces the expression of IL-6 and the subsequent activation of STAT3." (PMID 38203626, 2023). "Manganese plays an important role in the anti-tumor immune response of cGAS-STING, which can improve the efficacy of clinical immunotherapy and is involved in some enzymes, such as pyruvate carboxylase and arginase in mitochondria." (PMID 38004195, 2023). "First, radiation induces cell death, which results in cytosolic DNA accumulation, and enhances antigen release in the tumor to activate the production of type I interferon (IFN) genes via the cGAS/STING pathway." (PMID 36742293, 2023). "cGAS-STING pathway exerts important effect to enhance anti-tumor immune response and cancer biotherapy efficacy." (PMID 37051596, 2023).
tumor (continued). "cGAS/STING mediated immunity is linked to the anti-tumor response, but how tumor-intrinsic cGAS signals are countered during tumorigenesis and immune evasion is poorly understood." (PMID 37193698, 2023). "Previous studies have demonstrated that ionizing radiation-mediated tumor regression is dependent on the activation of the cGAS-MITA/STING axis in dendritic cells (DCs)." (PMID 37932533, 2023). "Bio-MnO2 NPs not only sensitized RT to stimulate cGAS-STING signaling but also relieved tumor hypoxia and generated ROS with the release of Mn2+ and oxidation of hydrogen peroxide into oxygen." (PMID 37514189, 2023). "Inducing pyroptosis and activating the cyclic guanosine monophosphate-adenosine monophosphate synthase/interferon gene stimulator (cGAS/STING) signaling pathway to upregulate innate immunity have become an emerging strategy for enhancing tumor immunotherapy." (PMID 37342347, 2023). "Herein, we revealed the promising potential of tumor microenvironment-driven gas therapy in cGAS-STING pathway activation." (PMID 37221157, 2023). "cGAS–STING signalling has been shown to have potent anti-cancer activities in a variety of mouse tumour models." (PMID 37534795, 2023). "Both H2S and CO stimulate mitochondrial dysfunction of tumor cells to induce the intracellular release of mtDNA, demonstrating the immunoadjuvant property of engaging cGAS-STING pathway." (PMID 37221157, 2023). "After recruitment of DCs to the immunogenic tumor site, the cGAS/STING pathway can be triggered inside the DCs, further enhancing antitumor IFN-1 signaling." (PMID 37420037, 2023). "NPPDT‐56MESS + L further induced the anti‐tumor immune responses to enhance the anti‐tumor effect via activating the cGAS‐STING pathway." (PMID 37807827, 2023). "After pyroptosis induced by NO, double‐stranded DNA is released from tumor cells, which contributes to Mn2+‐enhanced cGAS‐STING pathway." (PMID 37400368, 2023). "The release of cytosolic mtDNA instigated tumor-intrinsic production of IFNβ and ISGs via the cGAS/STING pathway." (PMID 38196632, 2023). "Tumor DNA (Tu-DNA) uptake by intratumoral DCs triggers the activation of the cytoplasmic DNA–sensing cGAS/STING pathway, which is required for type I IFN induction." (PMID 36821379, 2023). "Collectively, these studies suggest that CIN-driven activation of cGAS–STING is an important driver of tumour cell invasiveness and metastasis." (PMID 36876871, 2023). "Recent studies have revealed that Brivanib can inhibit angiogenesis and target cGAS to enhance the anti-tumor immune response." (PMID 38137387, 2023). "Based on CoNCDs’ good biocompatibility and therapeutic effect on the tumor, we then introduced the cGAS–STING agonist, and the combination of the CoNCDs and STING agonist significantly inhibited tumor growth, and no significant systemic toxicity was observed." (PMID 37762239, 2023). "As we previously reported, the expression of cGAS-STING in tumor cells was maintained at a high level in dMMR/MSI-H CRC, compared to pMMR/MSS CRC, due to less frequent methylation in the promoter region of STING especially." (PMID 37345163, 2023). "On the contrary, we found that treatment with GPC3144‐152 peptide in the co‐culture of CD8+ T cells with TYST or TYST‐sh‐cGAS cells significantly enhanced the levels of TBK1 and IRF3 phosphorylation in these tumor cells, even after silencing cGAS." (PMID 37986544, 2023). "The cGAS/STING pathway functions primarily as a tumor suppressor with respect to interferon (IFN) production and T-cell priming." (PMID 37354378, 2023). "Apart from leading apoptosis, the PARP inhibitor modulates the tumor microenvironment by activating the cGAS-STING pathway and, thus, enables low-dose CAR-T-cells with higher efficacy." (PMID 37627063, 2023). "We demonstrate that DNA‐PK and cGAS synergize for the production of type I IFNs and chemokines, thus dictating the composition of the tumor microenvironment." (PMID 36574362, 2023).
tumor (continued). "Cancer vaccines also activate the antitumoral properties of the cGAS/STING pathway utilizing tumor-derived MPs and DNA signaling." (PMID 37380989, 2023). "Our recent findings indicated that the expression of tumor cell-intrinsic cGAS-STING remained elevated in dMMR/MSI-H CRC, promoting increased infiltration of CD8+ T cells." (PMID 37345163, 2023). "The expression of cGAS was significantly higher in tumor cells of proximal colon than tumor cells of distal and rectum colons." (PMID 37345163, 2023). "Collectively, these results implicate cGAS/STING as an important immune sensor regulating RA‐mediated tumor cell immunogenicity." (PMID 36876644, 2023). "The cGAS/STING activation in tumor cells participates in antitumor immune response, while activation of the cGAS/STING pathway in host immune cells mainly contributes to tumor control." (PMID 37986544, 2023). "The near-ubiquitous presence of varying degrees of CIN among cancers suggests that tumour cells experience selective pressures that should compel them to overcome cGAS–STING activation and immune surveillance." (PMID 36876871, 2023). "DDR-targeted therapies including ATM inhibitors have been shown to convert the “cold tumor” into “hot tumor” in some cancer types, through inducing cGAS/STING-mediated innate immunity." (PMID 36778120, 2023). "In PDX-287R, carboplatin treatment initially induced apoptosis within the tumor cells, accompanied by a pro-inflammatory response, increased cGAS-STING signaling and increased expression of chemokines, including CXCR3 ligands for T cell chemotaxis." (PMID 37660083, 2023). "When the radiation is delivered at a high dose, induced Trex1 degrades the accumulated cytoplasmic DNA in irradiated tumor cells, which precludes the activation of cGAS-STING-IFN signaling and dampens immune responses." (PMID 37122745, 2023). "These support the notion that activation of the cGAS/STING signaling in the tumors is crucial for recruiting antitumor CTLs into the tumor environment to inhibit the growth of tumors." (PMID 37986544, 2023). "PARPi has been verified to elicit cGAS-STING signaling in both tumor and immune cells to increase immune infiltration and pro-inflammatory signaling." (PMID 37122745, 2023). "Several previous studies have established the significance of the cGAS-STING pathway in tumor cells for activating immune cells in the tumor microenvironment (TME) in CRC." (PMID 37345163, 2023). "Tumor cells can initiate NFκB signaling, increasing IL-8 and reducing IL-6 secretion, mtDNA can activate cyclic GMP-AMP synthase and inflammasome pathways." (PMID 37292196, 2023). "built a MnO2 contained M@P@HA nanoparticles as novel cGAS-STING amplifiers to enhance the innate immunotherapy against tumor." (PMID 37153576, 2023). "Immune and tumor cells use the cGAS-STING mechanism to sense and respond to genomic instability, DNA damage, and mitochondrial dysfunction induced by extra- and intracellular stresses." (PMID 36861445, 2023). "Various genes, including KIF2B/C, PICH, MASTL, PRC1, APOBEC3A, and CCAT2 lncRNA, have been shown to modulate tumour immunity through their interactions with the cGAS-STING pathway." (PMID 38067140, 2023). "The fact that cGAS-STING has complex consequences during tumor progression suggests that our understanding of the two sides of cGAS-STING in cancer progression is important for advancing cancer therapeutic strategies." (PMID 37965570, 2023). "Taking the advantages of high stability and biocompability, MnO2 nanoparticles have been demonstrated to show strong anti-tumor activities by releasing manganese ions in the tumor environment to enhance the activation of cGAS-STING pathway." (PMID 37153576, 2023).
tumor (continued). "This, together with reduction of the dsDNA content in the tumor cells that attenuates the cGAS/STING pathway and consecutively the INFgamma-dependent immune activation, contributes to immune suppression." (PMID 37152024, 2023). "As the sensor of cytosolic DNA, the cyclic GMP-AMP synthase (cGAS)-stimulator of interferon genes (STING) pathway plays a critical role in regulating anti-tumor immunity and cell death." (PMID 37781035, 2023). "This way, the cGAS‐STING pathway is activated to induce anti‐tumor immune responses and ultimately enhance anti‐cancer activity." (PMID 37807827, 2023). "The tumor cells need to evade this signaling pathway detection to survive in the harsh living environment; thus, the cGAS-STING axis was observed to be disrupted in tumors." (PMID 37834184, 2023). "From a translational perspective, these findings provide what is, to our knowledge, the first mechanism-based, systemic pharmacological strategy to induce tumor-specific, cGAS/STING-independent Type I IFN production." (PMID 36918588, 2023). "One such mechanism involves the induction of a robust type I interferon (IFN) response mediated by cGAS-STING activation by tumor-derived DNA in immune cells and tumor cells themselves." (PMID 38203626, 2023). "By interacting with exogenous DNA from tumor cells or endogenous DNA leakage from mitochondria, activated cGAS promotes the formation of cGAMP and further activates STING signaling." (PMID 36761762, 2023). "Analyses of hot tumors have revealed that cDC1 (CD24+XCR1+ DCs in mice, CD141+ XCR1+ DCs in humans) tumor-infiltrating dendritic cells (TIDCs) recognize tumor-derived DNA in the cytoplasm via cGAS." (PMID 37046775, 2023). "Further investigation is needed to understand the role of tumor-cell intrinsic cGAS-STING, not only in the activation of immune cells in the TME but also in tumor cell proliferation in CRC." (PMID 37345163, 2023). "It is becoming increasingly clear that cGAS–STING pathway functions in tumours extend beyond the induction of tumour-suppressive inflammation." (PMID 36876871, 2023). "in 2018 showed that chromosomal instability in tumor cells can lead to activation of the cGAS/STING pathway." (PMID 37420037, 2023). "Cytosolic dsDNA sensed by cGAS stimulate cGAS-STING signaling to trigger anti-tumor immune response, which results in better survival." (PMID 37215984, 2023). "We have recently reported that irradiation can induce remodeling of the tumor-microenvironment through tumor cell-intrinsic expression of cGAS-STING19." (PMID 37582945, 2023). "Hypermethylation of cGAS or STING promoter regions is present in several types of tumor samples, resulting in cGAS or STING repression." (PMID 37965570, 2023). "In age-related tumors, G3BP1 activates the NF-κB and STAT3 pathways via cyclic GMP-AMP synthase (cGAS), promoting the senescence-associated secretory phenotype (SASP) and stimulating the migration of tumor cell." (PMID 37179344, 2023). "It has been reported that activation of the cGAS/STING signaling in the tumor cells promotes the recruitment of CTLs into the tumor microenvironment and can enhance the antitumor responses of CTLs." (PMID 37986544, 2023). "This study provides feasible reference on the design of cGAS/STING enhancing formulations for tumour immunotherapy." (PMID 38264691, 2023). "Recent work has reported that double‐stranded DNA is recruited in healthy tumour cells to MVs by ARF6 in association with the cytosolic DNA sensor, cyclic guanosine monophosphate‐AMP sensor (cGAS)." (PMID 37294158, 2023). "Knocking down of cGAS significantly suppressed tumor growth of Hep3B cells in a mouse xenograft model, which was ultimately rescued by the restored expression of cGAS, suggesting that the cGAS is important for tumor growth in HCC." (PMID 37834184, 2023).